Y_RNA (Y RNA )
Gene: Miscellaneous RNA gene on chromosome 8 (102,950,467 to 102,950,564, reverse strand). Ensembl gene ENSG00000201216.
Homologues: Orthologues: chimpanzee Y_RNA (100% identical), macaque Y_RNA (91% identical). Paralogues in human: RNY4P25 (86% identical), RNY4 (85% identical), RNY4P10 (84% identical), RNY4P6 (84% identical), RNY4P19 (83% identical), RNY4P7 (83% identical), Y_RNA (83% identical), RNY4P14 (82% identical), RNY4P36 (82% identical), Y_RNA (82% identical), RNY4P37 (81% identical), RNY4P9 (81% identical), and 88 more.